BRCA1 (BRCA1 DNA repair associated)
Diseases named in the same sentence as BRCA1 in open-access papers (continued):
Sharing a sentence is not in itself a finding about the gene and the disease.
tumor (continued). "BRCA1/2-deficient tumor cells can become resistant to PARP inhibitors by restoring HR repair and/or by stabilizing replication forks." (PMID 32316968, 2020). "We report the rate of tumor BRCA1/2 mutations, optimal tissue requirements and challenges encountered such as variable quality of tissue samples and success rates following repeat testing." (PMID 33233347, 2020). "The viability of synthetic lethality strategies has been demonstrated with the use of poly [ADP-ribose] polymerase (PARP) inhibitors, since tumor cells harboring BRCA1/2 mutations are 1000 times more sensitive to PARP inhibition than wild-type counterparts." (PMID 32580485, 2020). "PARP‐inhibitors are the first class of MTA that targets mutations in tumor suppressor genes (BRCA1 and BRCA2)." (PMID 32881420, 2020). "In our cohort, 12 of 13 cases with BRCA1 pathogenic variants and 5 of 21 (23.8%) of the controls developed a TN tumor, whereas the prevalence in the literature is 80 and 14%, respectively." (PMID 32727387, 2020). "Given that tumor BRCA1/2 testing identifies both germline and somatic mutations, we endorse universal tumor testing in newly diagnosed HGSC patients." (PMID 33233347, 2020). "In multivariate regression analyses including age at diagnosis and tumor stage, overexpression of this pathway was also detected significantly associated with BRCA1/2 mutations (P = 0.013)." (PMID 32400970, 2020). "For these samples, it is likely that BRCA1/2 biallelic loss occurred relatively late in the tumor progression stage which results in an insufficient number of HRD-associated mutations for clear HRD classification by CHORD." (PMID 33149131, 2020). "Due to the defective activity of their HR DNA repair machinery, BRCA1/2-mutated HGSOCs exhibit a higher tumor mutational burden, thus expressing more tumor-specific neoantigens and harboring increased amounts of TILs and PD-1/PD-L1." (PMID 32455819, 2020). "Given our finding that NOTCH1 promotes BRCA1-deficient tumour growth by activating ATR–CHK1 and inducing EMT, we inhibited the ATR/CHK1 pathway in combination with a low dose of cisplatin to effectively kill TNBC in our mouse model and PDX model." (PMID 32591500, 2020). "This is the case with tumours associated with mutations in one copy of either BRCA1 or BRCA2; in these tumours, PARP1/2 inhibitors lead to an accumulation of DNA SSBs, which are converted during replication to irreparable toxic DNA double-strand breaks." (PMID 33050515, 2020). "CX-5461 was also found to be selectively lethal in BRCA1/2 deficient tumours possibly via stabilization of G-quadruplex structures and is currently in clinical phase I for BRCA1/2-deficient tumours." (PMID 32857853, 2020). "Its overexpression is linked to the inhibition of BRCA1 gene by means of hypermethylation which is a highly predisposing factor to TNBC, as BRCA1 is a tumor-suppressing gene." (PMID 32722276, 2020). "Together these findings underline the potential of exploiting immune dysfunction in the context of HR deficiency, notably in BRCA1/2 mutant tumours, and TNBC more generally." (PMID 32471999, 2020). "Tumor cells in patients carrying a germline mutation in BRCA1 are sensitive to cytotoxic drugs that cause DNA double strand breaks." (PMID 32175521, 2020). "The VAF of 77.8% for BRCA1 variant (p.L63*) seen in the HGSC-1 tumour indicates a loss of heterozygosity (LOH) in the tumour or the presence of uniparental disomy with a germline mutation." (PMID 32724113, 2020). "High throughput sequencing methods, such as Tumor Mutation Burden, somatic detection of BRCA1 and BRCA2 single nucleotide variants and copy number variations that can address patient to targeted therapeutic approaches, are strongly influenced by DNA integrity." (PMID 32140450, 2020).
tumor (continued). "Up to three alterations were observed in DDR genes within a single tumor, and this tumor also exhibited a BRCA1 germline mutation (p.C61G)." (PMID 32719318, 2020). "It has been shown previously that germline BRCA1/BRCA2 mutations leave a recognizable imprint on a tumor’s mutational landscape." (PMID 32997669, 2020). "The loss of wild type BRCA1 (or loss of heterozygosity) gene in tumor samples reveals its role as a tumor suppressor gene." (PMID 33716731, 2020). "Chlorambucil and cisplatin are equally effective in targeting specifically BRCA1/2‐deficient tumours." (PMID 31273933, 2019). "All pathogenic CNVs were confirmed in the five matched FFPE tumor samples from patients carrying known pathogenic germline mutations and we additionally identified somatic loss of the second allele in BRCA1/2." (PMID 31029168, 2019). "In an univariate analysis of clinicopathological factors associated with BRCA1-mutated BC versus the WT subtype, tumor grade, ER, PR, and expression of CK5, CK14, and CLDN3 were found to be independent parameters." (PMID 31307407, 2019). "Many tumours had BRCA1/2 (18%) variants, including confirmed somatic mutations in haemangioblastoma." (PMID 32082376, 2019). "In fact, TNBC represents the predominant tumor type in patients with BRCA1 mutations, accounting for 71% (range 42-100%) of tumors, while TNBC has been diagnosed in only 25% of patients with germline BRCA2 mutations." (PMID 31379942, 2019). "BRCA1 protein plays a critical role in error-free DNA repair and its mutation is associated with global chromosome instability and tumor formation." (PMID 31273285, 2019). "Our work demonstrates the specific toxicity of chlorambucil to BRCA1/2‐deficient human cells and xenograft tumours." (PMID 31273933, 2019). "The three tumor samples (P26, P28, P29) had homozygous pathogenic variants in either BRCA1 or BRCA2 based on variant frequencies, indicating LOH in these samples." (PMID 31029168, 2019). "The striking sensitivity of breast related cancer antigens 1 and 2 (BRCA1/2) deficient tumour cells to poly (ADP-ribose) polymerase PARP inhibition have been demonstrated in 2005." (PMID 31374917, 2019). "HGSOC patients with BRCA1/2 mutations had significantly higher peritoneal tumour load and significantly increased frequency of bulky lymph nodes at diagnosis than those with wild-type BRCA genes." (PMID 31064392, 2019). "We have found that expression of the CSC-associated markers CD44 and ALDH1A is significantly increased in tumor cells with mutated or down-regulated BRCA1." (PMID 31273285, 2019). "Another study reports the interaction with and activation of FADD promoter by BRCA1, suggesting that BRCA1 loss or inactivation in a tumor can cause reduced levels of FADD that in turn desensitize cells to apoptosis." (PMID 31569512, 2019). "Sensitivity of BRCA1/2‐mutated tumours to platinum compounds has been validated in multiple pre‐clinical and clinical studies." (PMID 31273933, 2019). "The authors of the genetic study anticipated that a decreased amount of OGG1 in the BRCA1-deficient tumour is likely to sensitize it to PARPi therapy." (PMID 31329989, 2019). "The inactivation of BRCA1 or BRCA2 due to somatic mutations or BRCA1 promoter methylation is also observed in these tumor types." (PMID 31727117, 2019). "BRCA1 is a key tumour suppressor that plays an important role in DNA repair and reduced BRCA1 expression is associated with breast and ovarian cancer." (PMID 30778069, 2019). "In OC, diagnosis occurred 11–12 years earlier in all HBOC risk groups than in the general population, although only BRCA1-associated tumors were mostly bilateral and more advanced in tumor development." (PMID 31771539, 2019). "As a result, tumor cells harboring HR deficiency are more sensitive to PARPi therapy than normal cells (e.g. over 1000 times in BRCA1/2 mutated tumor cells)." (PMID 31737426, 2019).
tumor (continued). "Pathogenic variants in BRCA1/2 were identified in four of these 11 samples, including the patient from whom non-tumor tissue was analyzed (P27)." (PMID 31029168, 2019). "Due to abdominal relapse, she underwent right hemicolectomy in October 2017; tumor sample analysis revealed somatic BRCA1 mutation." (PMID 31850198, 2019). "Same as previous study, the BRCA1/2 germline mutations were significantly associated with HBOC‐related tumor or family history." (PMID 30972954, 2019). "We selected PDX-110 (BRCA1-mutated) to examine the impact of chemotherapy on tumor heterogeneity, as this PDX was highly responsive to cisplatin therapy." (PMID 30770823, 2019). "It is not uncommon for tumor-suppressing factors to rely on a secondary mutation to initiate tumor development, and in fact, this trend is also observed in BRCA1, BRCA2, and RAD51C mutations." (PMID 31775907, 2019). "In conclusion, this research combines both pedigree and tumor data to identify the main variables associated with the presence of a BRCA1 or BRCA2 germline mutation." (PMID 31244284, 2019). "Treatment with the PARP inhibitor talazoparib triggered ISG expression in these BRCA1-deficient tumours, as demonstrated by quantitative RT-PCR analysis of tumor RNA." (PMID 31316060, 2019). "The best-known disease-associated examples of defective components of homologous recombination repair are the breast- and ovarian-associated tumor suppressor genes BRCA1 and BRCA2." (PMID 30684955, 2019). "Although PARP1 constitutes a promising target in the treatment of tumors harboring deficiencies in BRCA1/2—mediated homologous recombination (HR), some tumor cells survive, resulting in disease relapse." (PMID 31615159, 2019). "TNBC is associated with younger age (<50 years) at diagnosis and BRCA1 mutation, and by the time of diagnosis have larger tumor size, higher grade tumor and the worst prognosis." (PMID 30678106, 2019). "Five pathogenic/likely pathogenic alterations (BRCA1 n = 4 and BRCA2 n = 1) and three VUS in BRCA1 were detected in the tumor specimens only and were considered somatic mutations." (PMID 31653094, 2019). "Germline BRCA1/2 status was available for 62 patients, including 28 cases with tumor BRCA status positive (23 pathogenic/likely pathogenic alterations and five VUS)." (PMID 31653094, 2019). "In line with previous findings in BC, we noted that RANKL expression was particularly elevated in BRCA1/2 mutated OC as compared to BRCA1/2 wild-type (wt) tumours." (PMID 31181781, 2019). "The BRCA1 BRCT domain is critical for tumor suppression, and a significant portion of germline mutations can be found in this region." (PMID 31827092, 2019). "For example, the tumor of patient 18 harbored only one BRCA1 allele, which carried the loss of exon 12 to 18 that was identified in a heterozygous state in blood." (PMID 31029168, 2019). "PARP inhibition causes synthetic lethality in combination with severe HR deficiency such as of tumor cells from BRCA1 or BRCA2 mutation carriers upon inactivation of the wild‐type allele." (PMID 31347298, 2019). "Other tumor-associated genes identified in our RNA-seq data which were differentially regulated in the BRCA1 organoids include NOTCH and ALDH1." (PMID 31771627, 2019). "Breast cancer type 1 susceptibility protein (BRCA1) is a nuclear protein that functions as a tumor suppressor with distinct patterns of cell-cycle-regulated expression and is hyperphosphorylated to sense DNA-damage, in order to direct DNA repair." (PMID 31480737, 2019). "The BRCA1 gene encodes a 220-kDa nuclear phosphoprotein (BRCA1) that functions as a tumor suppressor through involvement in DNA damage repair, cell cycle control, transcriptional regulation, apoptosis, and mRNA splicing." (PMID 31652854, 2019). "Initially identified in samples with germline and somatic BRCA1/2 variants, more recently it has also been found in tumours with epigenetic silencing of BRCA1 or homologous deletions of BRCA1/2." (PMID 30763338, 2019).
tumor (continued). "We identify chlorambucil as the highest scoring hit from this screen, which selectively eliminates BRCA1/2‐deficient cells and tumours, including olaparib‐resistant and cisplatin‐resistant ones." (PMID 31273933, 2019). "These and other findings have suggested that breast tumorsarising in BRCA1 mutation carriers are associated with moreaggressive tumor characteristics compared to BRCA2 mutationcarriers." (PMID 31067289, 2019). "A unique and therapeutically useful feature of tumor cells with HR deficiencies (e.g., BRCA1 mutations) is an increased sensitivity to PARP inhibitors." (PMID 30616689, 2019). "In all, these conclusions led us to propose that tumor-related BRCA1 mutations are associated with an IFN-γ gene signature, partly regulated through altered H3 acetylation." (PMID 31840082, 2019). "In large agreement with this notion, RAD52 inhibitors exerted synergistic activity with PARPi against BRCA1-deficient tumor cells." (PMID 31921645, 2019). "Palb2-, Brca1- or Brca2- deficient tumor cells in comparison to KPC or Palb2flox/+-KPC tumor cells are exquisitely sensitive to DNA damage inducing agents, including Olaparib, MMC and Cisplatin." (PMID 31877165, 2019). "Compared with germline BRCA1/2 variant testing, the analysis on tumor tissue allow to identify also somatic alterations." (PMID 31653094, 2019). "Drugs that induce DNA lesions are routinely used in the clinic to treat BRCA1/2‐deficient tumours (e.g. cisplatin and PARP inhibitors)." (PMID 31273933, 2019). "It was found that SET tumours frequently associate with BRCA1 mutations and contain a greater number of tumour-infiltrating lymphocytes compared to typical HGSOC." (PMID 30813239, 2019). "In many cases, tumor cells become resistant to treatment due to a variety of mechanisms, including secondary mutations restoring function of BRCA1/2, or overexpression of the P-glycoprotein efflux pump, which limits the delivery of the drug into the cells." (PMID 31615159, 2019). "Among the 221 cases successfully analyzed, 62 (28.1%) cases harbored tumor BRCA1 or BRCA2 pathogenic/likely pathogenic mutations." (PMID 31653094, 2019). "After correcting the size of the genome in each tumor to account for copy number alterations, we find that the BRCA1-mutated samples have larger genomes than BRCA2-mutated or sporadic tumors (Wilcoxon test p = 3.2 × 10− 3)." (PMID 31182087, 2019). "BRCA1 was mutated via frameshift deletion in one ASL tumor and via nonsense mutation in one HCC tumor in this cohort, representing what we believe to be the first known reports of mutation of this gene in ASL and HCC." (PMID 31796844, 2019). "Monoallelic BRCA1/2 mutations require a ‘second-hit’ to the unaffected allele, since only tumours with complete abrogation of BRCA1/2 are targetable with PARPi." (PMID 31591445, 2019). "Familial cases usually are found to be due to germline mutations in the tumour-suppressor genes BRCA1 and BRCA2, which also contribute increased risk of developing breast cancer in these same families." (PMID 30813239, 2019). "A lasso logistic regression model identified six distinguishing mutational signatures and HRDetect identified BRCA1/2-deficient tumours with 98.7% sensitivity." (PMID 29867226, 2018). "Drugs targeting the poly-(ADP-ribose) polymerase (PARP) enzymes PARP1 and PARP2 cause synthetic lethality in tumour cells with homologous recombination (HR) defects, including those with loss-of-function mutations in the BRCA1 or BRCA2 tumour suppressor genes." (PMID 29748565, 2018). "Our finding, for the first time, demonstrates that estrogen promotes BRCA1-deficient tumor initiation and progression by stimulation of cell proliferation and activation of EMT, which are dependent on AKT activation and independent of ER." (PMID 29996906, 2018). "Mutational inactivation of BRCA1/2 renders tumours deficient in homologous recombination DNA damage repair (HRR)." (PMID 29298688, 2018).
tumor (continued). "Women carrying germline mutations in BRCA1 have a substantially elevated risk of breast cancer and their tumours typically have distinctive histological features." (PMID 29491469, 2018). "Our findings will facilitate a better understanding of basal-like and BRCA1-associated tumours and provide tools for greater patient prognostication." (PMID 30323900, 2018). "The breast cancer type 1 susceptibility gene BRCA1 encodes a large protein of 1863 amino acids that acts as a tumor suppressor." (PMID 29996917, 2018). "PARP1-positivity was significantly associated with sex of patients (P = 0.038), higher tumor stage (P = 0.024), higher histologic grade (P = 0.008), and the expression of γH2AX (P = 0.001), BRCA1 (P = 0.009), and BRCA2 (P = 0.001)." (PMID 29784019, 2018). "This study reveals for the first time that estrogen promotes BRCA1-deficient tumor initiation and progression by stimulation of cell proliferation and activation of EMT, which are dependent on AKT activation and independent of ER." (PMID 29996906, 2018). "Our experiments also showed that PARP1 mutation can be tolerated in certain BRCA1 mutant, PARPi-sensitive tumour cells." (PMID 29748565, 2018). "Estrogen activates the PI3K/AKT pathway in ER-negative breast cancer cells, and promotes survival of Brca1-deficient tumor cells, which stimulate tumor growth." (PMID 29996906, 2018). "By parallel sequencing, all tumor manifestations were analyzed for BRCA1 and BRCA2 mutation and were further analyzed using a panel of 12 other genes resulting altogether in a total of 452 amplicons." (PMID 29855275, 2018). "Toxicity from PARPi within the BRCA1/2-deficient tumor cells is much higher than in the surrounding BRCA1/2-proficient tissue." (PMID 30551670, 2018). "We discovered that estrogen activates EMT in a subset of Brca1-deficient tumor cells that maintain epithelial features, and enhances the number of CSCs, promoting ER-negative basal-like tumor progression and metastasis." (PMID 29996906, 2018). "In the present study, we demonstrated that estrogen activates the Akt pathway not only stimulating proliferation but also promoting EMT in ER-negative, BRCA1-deficient tumor cells, which further enhances tumor progression." (PMID 29996906, 2018). "We collaborated with 10 laboratories testing BRCA1/2 in tumors to compare different approaches to identify clinically important variants within FFPE tumor DNA samples." (PMID 29215764, 2018). "In women with a somatic BRCA1/2 mutation in the tumour tissue only, biallelic LOF occurs through mutations and/or epigenetic silencing in both wild-type alleles and is often clonal." (PMID 29464354, 2018). "We demonstrate that estrogen promotes BRCA1-deficient tumor initiation and progression by stimulation of cell proliferation and activation of EMT, which are dependent on AKT activation, but independent of ER." (PMID 29996906, 2018). "The loss of BRCA1, one of the most widely studied tumor-suppressor proteins, is transmitted hereditarily." (PMID 30652068, 2018). "The susceptibility to CM and UM associated with BRCA1/BRCA2 is an example of melanotic tumours being part of a spectrum of tumours associated with well characterised cancer predisposition syndromes." (PMID 29641532, 2018). "We found that AZD5363 drastically inhibited E2-enhanced expression of p-4Ebp1, p-mTor, and p-Gsk3β, and that of Vim and p-Fra1, suggesting that AZD5363 efficiently suppresses estrogen-enhanced Akt pathway and EMT program in Brca1 deficient tumor cells." (PMID 29996906, 2018). "We isolate PARP1 mutants from tumour cells with BRCA1 exon 11 mutations and demonstrate that residual BRCA1 function in these cells allows tolerance of PARP1 loss of function, despite the synthetic lethal relationship between these genes." (PMID 29748565, 2018).